FOXP3 (forkhead box P3)
Diseases named in the same sentence as FOXP3 in open-access papers (continued):
Sharing a sentence is not in itself a finding about the gene and the disease.
tumor (continued). "Conversely, higher counts of FOXP3+ regulatory T‐cells and CD68+ macrophages have been linked to an immune‐exclusion phenotype and tumor recurrence." (PMID 38017652, 2024). "Tumors can transform DCs into FOXP3+ Tregs, and DCs can also secrete IL-10 to induce the transformation of T cells into Tregs, thus revealing that DCs can promote tumor development." (PMID 39263534, 2024). "All MSI-H CRCs were subjected to digital pathology-based quantification of CD3 + /CD8 + /CD4 + /FoxP3 + /CD68 + /CD204 + /CD177 + tumor-infiltrating immune cells using whole-slide immunohistochemistry." (PMID 39235590, 2024). "Taken together, these results suggest that the constitutive elimination of CD11chi DCs alters the composition of CD4+Foxp3+ Treg cells in lymphoid tissues under homeostatic and tumor-bearing conditions." (PMID 39206204, 2024). "We also analyzed the intratumoral infiltration of regulatory T cells (Tregs, CD3+CD4+ Foxp3+), given Tregs’ role in restraining anti-tumor immune responses of CTLs." (PMID 39613774, 2024). "An increase in tumor-infiltrated Foxp3+ Tregs was also found in the untreated control group consuming a high dietary Zn." (PMID 39247196, 2024). "In summary, we demonstrated that overexpression of IFI27 inhibits BCa growth by reducing the infiltration of Treg cells in the tumor parenchyma through the suppression of FOXP3 expression in Treg cells." (PMID 39668835, 2024). "Regulatory T cells (Tregs), a subgroup of CD4+ T cells that express the FoxP3 gene and have immunosuppressive properties, are found in high numbers in the tumor microenvironment (TME) of different types of malignancies." (PMID 38509593, 2024). "CD4+CD25+FOXP3+ Tregs are associated with poor prognosis in patients with ESCC, suggesting that CD4+CD25+FOXP3+ Tregs are crucial for enhancing the invasive ability of TC and facilitating tumor escape." (PMID 39264227, 2024). "The infiltration density of CD68+TAMs and CD4+FoxP3+Tregs in the tumor area of Mφ-Siglec-15+PD-L1+ patients were higher than that of Mφ-Siglec-15−PD-L1− patients (p < 0.05)." (PMID 38072971, 2024). "As the main immunosuppressive cells, the number of FOXP3 regulatory T cells (Tregs) within the tumor following PAC-SABIs treatment was found to be significantly decreased." (PMID 38971872, 2024). "M1/M2 macrophages, N1/N2 neutrophils, CD4+ T cells (T-helper), CD8+ T cells (T-cytotoxic), FOXP3+CD4+ Tregs, and antigen-presenting DCs are widely known infiltrating immune cells and are implicated in a spectrum of tumor pathologies." (PMID 38730579, 2024). "Based on these observations we conclude that INHBA(+) fibroblasts play a role in shaping the tumor immunosuppressive microenvironment by inducing expansion of the pro-tumorigenic CD4( +) CD25(+) FOXP3(+) Tregs." (PMID 38360876, 2024). "It was also demonstrated that FOXP3 promotes tumor growth and metastasis in tumor cells in NSCLC by activating the Wnt/β-catenin signaling pathway and epithelial–mesenchymal transition (EMT)." (PMID 38674427, 2024). "In the splenectomy group, they additionally observed a lower ratio of effector T cells (CD8 + /CD4 +) to immunosuppressive regulatory T cells (FOXP3 +), suggesting an impaired anti-tumor immune response." (PMID 39710775, 2024). "The increased FOXP3 expression in cancerous tissues was primarily localized in both the nucleus and the cytoplasm of tumor cells." (PMID 38674427, 2024). "Upregulation of the H3K18la level in the promoter region of the FOXP3 gene can reduce the anti-tumor function of Natural killer T-like cells by promoting FOXP3 expression." (PMID 39876842, 2024). "By selectively suppressing FOXP3 in Tregs, we offer a potential strategy to enhance anti-tumor immunity." (PMID 39772246, 2024). "Studies have reported that FoxP3 in cancer cells functions as a tumor suppressor and inhibits the expression of several oncogenes." (PMID 39150932, 2024).
tumor (continued). "In ESCC patients undergoing neoadjuvant chemotherapy, the PD-L1 status of tumor cells in positive LN tissues and the FOXP3/CD8 ratio in primary tumors are identified as prognostic factors for overall clinical outcomes." (PMID 39399490, 2024). "At the study evaluation timepoint of 2 h post H-FIRE, we observed differential gene expression changes in the genes IDO1, IL6, TNF, CD209, and FOXP3 in treated tumor regions relative to paired untreated tumor regions." (PMID 39335552, 2024). "In most cancers, highly CTLA-4-expressing Fr.II eTregs are the predominant tumor-infiltrating Foxp3+Tregs." (PMID 39290699, 2024). "Since NK cells can express CTLA4 and CD2548,49, we utilized anti-OX40 Abs, which efficiently deleted the FoxP3+ CD4 T cells within the tumor while leaving NK cells intact." (PMID 38267402, 2024). "The prognostic significance of FoxP3+ tumor infiltrating Tregs in cancer also remains arguable as it is further influenced by tumor site, molecular subtype, and tumor stage." (PMID 38482021, 2024). "A vital subgroup of CD4 T-cells known as regulatory T-cells (Tregs) are typified by the CD4 + CD25 + Forkhead box P3+ (FoxP3+) phenotype and are capable of modulating peripheral tolerance as well as responses to foreign and tumor antigens." (PMID 38672732, 2024). "Tumours with positive PD-L1 IC expression were more likely to have high Foxp3+CD4+ T cell infiltration in tumour islets, as well as tumours with positive PD-L1 TPS, IC, or CPS were more likely to have low IL-17A+CD4+ T cell infiltration in the tumour stroma." (PMID 39409156, 2024). "Further analysis of the relationship between FOXP3 and tumor infiltration stages revealed that FOXP3 abundance was up-regulated at T3 and T4 stages compared to T1 and T2 stages in BCa." (PMID 39668835, 2024). "Consistently, we observed a similar ratio of CD8/FOXP3 positive cells in ER-low and ER-neg tumor specimens, suggesting a similar polarization of the TME." (PMID 39083015, 2024). "Consistently, comparisons of LGALS9 and FOXP3 mRNA levels, which represent tumor galectin‐9 and Tregs, respectively, in the TCGA LUAD dataset also revealed a positive correlation." (PMID 38528665, 2024). "Unlike FoxP3+ CD4+ T cells, which typically exhibit regulatory functions that can suppress anti-tumor immune responses, FoxP3- CD4+ T cells can enhance anti-tumor activity." (PMID 39335203, 2024). "Conversely, the combined therapy caused a statistically significant increase in the number of CD8+ T cells and CD80+ M1-like macrophages and a reduction of FoxP3+ Treg in the tumor area compared to the control group." (PMID 38824552, 2024). "Findings show that the extract controlled and combatted BC, and suppressed the expression of Foxp3+Treg cells within tumor tissue." (PMID 39050852, 2024). "High levels of tumor necrosis factor receptor type II (TNFR2) are preferentially expressed by immunosuppressive CD4+Foxp3+ regulatory T cells (Tregs), especially those present in the tumor microenvironment, as initially reported by us." (PMID 39247806, 2024). "Nevertheless, little is known about how Foxp3, a crucial regulatory component in tumor immunology, affects the immune response that relies on Foxp3+Treg cells in the tumor microenvironment." (PMID 38919615, 2024). "Regulatory T cells (Tregs) expressing transcription factor forkhead box P3 (FOXP3) are crucial for maintaining dominant self-tolerance and immune homeostasis, typically inhibiting anti-tumor immune reactions and supporting tumor progression." (PMID 39267195, 2024). "In cervical cancer, CD4Cre; STINGflox/flox mice carrying tumors exhibited slower tumor growth tendencies and fewer FOXP3+ cells but a higher proportion of CD8+ cells in the tumor tissue." (PMID 38523155, 2024).
tumor (continued). "PGE2 also reduces the expression of cytokines, i.e., INF-γ and IL-4, shifting the immune balance towards Th2 cells; in this way, it contributes to an increase in anti-tumour activity by promoting immunosuppressive cells such as regulatory CD4+CD8+FoxP3+ Tregs." (PMID 39120301, 2024). "Regulatory T (Treg) cells are immunosuppressive cells that are defined as Foxp3+ cells in mice, and these cells have been shown to promote tumor progression and metastasis through their suppressive functions." (PMID 38195889, 2024). "presented tumor grade and stage independent prognostic effect of FOXP3+ regulatory T-cells and CD4+ lymphocytes in 157 extrahepatic and 69 gallbladder CCA." (PMID 38751812, 2024). "Conversely, inhibitors that prevent USP7 from being deubiquitinated can reduce Foxp3+Treg’s ability to suppress the immune system, which can allow tumor cells to evade the immune system." (PMID 38919615, 2024). "Nevertheless, the prognostic role of FOXP3 needs to be clarified, as it strongly correlates with tumor location, molecular subtype and tumor stage." (PMID 38674427, 2024). "Further, the correlation between CD59 and Treg and/or MDSC in the tumor microenvironment (TME) has shown to be strongly associated with poor outcomes in CESC, GBM, HNSC, and STAD as these tumors express high FOXP3 compared to KIRC." (PMID 39518137, 2024). "To further explore the possible mechanisms by which FH affects therapeutic efficacy, we analyzed the expression of CD8, FOXP3, and PD-L1 in the subcutaneous tumor tissue of Fh1 knockdown mice by flow cytometry." (PMID 38398104, 2024). "The proportion of ADR+ cells in CD4+Foxp3+ Tregs in the spleen, liver, and tumor tissues was analyzed by FACS." (PMID 39247806, 2024). "Our data also show that the balance between CD45RO+ and FoxP3+ cells in the tumor area has an important prognostic value." (PMID 38887294, 2024). "In a similar vein, in situ tumor formation models demonstrated that the downregulation of FOXP3 resulted in a notable decrease in the proliferation of U87 cells in situ." (PMID 38561331, 2024). "The number of Foxp3(+) Treg cells per field in the tumor samples was reduced with treatments as well, indicating that the reduction of acidification of the tumor microenvironment is involved in the regulation of Treg infiltration." (PMID 38672607, 2024). "Single-cell multiplexed imaging analysis revealed RSS2 had high stromal content and low FOXP3+ Tregs infiltration in the tumour." (PMID 38532103, 2024). "Recent anisomycin studies have shown that FOXP3 expression in mice and human tumor cells is therapeutic." (PMID 38827026, 2024). "Lnc-EGFR expression in Tregs was found to be strongly related to EGFR/Foxp3 expression and tumor development but inversely related to IFN-γ expression." (PMID 39257589, 2024). "T cell phenotypes were characterized and CD3+CD8-FoxP3- T cells were found to be the predominant tumor-infiltrating subtype while CD3+FoxP3+ T cells and CD3+CD8+ T cells showed similar densities." (PMID 38375478, 2024). "Consistently, the ratio of FOXP3+ cell to GZMB+ CD8+ T cell in MLN tumor area was higher than PT, suggesting that the immunosurveillance of the metastatic area in the lymph nodes was suppressed." (PMID 39236316, 2024). "LC3B correlated only with CD8+ cytotoxic T lymphocytes whereas, HMGB1 correlated with both local and peritumoral infiltrates involving FOXP3+ regulatory T cells and CD68+ tumor-associated macrophages." (PMID 39830522, 2024). "Expression of FOXP3 in tumor-infiltrating lymphocytes in the context of a prognostic marker is extensively studied in NSCLC." (PMID 38674427, 2024). "Specifically, P60 is a linear peptide capable of selectively binding to Foxp3, preventing its nuclear translocation and inducing an antitumor response in preclinical tumor models." (PMID 39598584, 2024).
tumor (continued). "For example, there is a significant correlation between FoxP3+ tumor-infiltrating lymphocytes (TILs) and total CD8+ T cells infiltration in triple-negative breast cancers." (PMID 38509593, 2024). "Some studies found that FoxP3 levels elevated in several tumor cell types, and indicated tumor progression." (PMID 39073490, 2024). "In contrast, CD4+ FoxP3+ regulatory T cells impede anti-tumor immunity by inhibiting cytotoxic T lymphocyte activation." (PMID 38560504, 2024). "In fact, blocking the CSF-1/CSF-1R axis results in a decrease in CD4+ Foxp3+ Tregs correlated with a reduction in tumor growth and enhances CD8+ T cell-mediated immunity in the sarcoma TME." (PMID 39457693, 2024). "Recently, we reported that high VEGFR2 expression in tumor tissue significantly predicted a poor outcome after PD‐1 blockade and closely correlated with the number of FOXP3‐expressing TILs in patients with advanced NSCLC." (PMID 38013668, 2024). "Effector Tregs are the predominant subtype of Tregs in tumor tissues and are characterized by coexpression of the transcription factor FOXP3 and the transmembrane protein CTLA4." (PMID 39227950, 2024). "We performed immunohistochemistry analyses using FOXP3 and CD163 antibodies in the validation cohort and found very pronounced macrophage infiltration (CD163) but hardly Treg infiltration (FOXP3) into the tumor site in some samples." (PMID 39669575, 2024). "Utilizing a mxIF panel of CD4, CD8, FOXP3, PD-1, Ki-67, and synaptophysin; T cells were appreciated throughout the tumor microenvironment of ONB." (PMID 38822345, 2024). "Among CD4+ T-cell populations, Tregs were the predominant subset and highly enriched in the tumor microenvironment of HBV-associated HCC, with the highest accessibility at the forkhead box P3 (FOXP3) loci." (PMID 38793588, 2024). "We counted the average number of c-FOXP3+E-Cadherin− tumor epithelial cells in five randomly selected fields at ×20 magnification per slide." (PMID 38047300, 2024). "To confirm our TAM and Treg cell transcriptional findings, we evaluated pretreatment tumour samples (n = 27) using multiplex immunofluorescence staining for pan-cytokeratin (tumour marker), FOXP3 (Treg cell marker), CD68 (macrophage marker) and PD-L1." (PMID 38418879, 2024). "Combining Mw with these therapies is associated with an increase in absolute number of tumor-infiltrating lymphocytes (TIL) and an increased frequency of CD4+ and CD8+ T cells with a decrease in FoxP3 and PD-1 expressing TIL." (PMID 39534596, 2024). "Increased numbers of CD4(+) Tregs expressing the transcription factor FoxP3 in malignant tumors promote tumor progression by suppressing effective anti-tumor immunity." (PMID 39409959, 2024). "USP7 has been shown to foster tumor growth by modifying the immunosuppressive properties of Foxp3 + Treg cells." (PMID 38834869, 2024). "The results obtained from the subcutaneous tumor formation model demonstrated that knockdown of FOXP3 significantly decreased the proliferation rate and weight of tumor tissues derived from U87 cells in vivo." (PMID 38561331, 2024). "These CD4 + FoxP3 + Eomes + T cells also express Granzyme B, a marker of cytotoxicity, and are able to clear the tumor in a CD8 + T cell-deprived mouse model." (PMID 38355394, 2024). "The frequencies of regulatory T cells (Treg) (CD4+ FoxP3+) and type 1 T helper (Th1) cells in tumor and TdLN were comparable between the genotypes." (PMID 38302493, 2024). "Higher levels of Treg cells, characterized by Foxp3-positive cells, were observed in tumor samples of KMT2Dmut patients than those of KMT2Dwt patients (p=0.025)." (PMID 39113693, 2024). "In tumor histological sections, a co-localization of mast cells and forkhead box P3 (FOXP3)-positive Treg cells have been recognizable and associated with a down-modulation of HLA class I on tumor cells and correlated with resistance to anti-PD-1 therapy." (PMID 38482531, 2024).
tumor (continued). "Angiogenetic proteins such as vascular endothelial growth factor (VEGF) and VEGFR create an immunosuppressive tumor microenvironment, with resultant increases in the expression of FOXP3 and the number of myeloid‐derived suppressor cells." (PMID 38013668, 2024). "We showed that suppressing FOXP3 expression in regulatory T cells (Tregs) using these vectors can reduce Treg activity, potentially enhancing anti-tumor immune responses." (PMID 39772246, 2024). "IHC staining for CD8 and FOXP3 in the same post-chemotherapy tumor bed and pre-chemotherapy biopsied samples was performed for nine patients (three from Group B1 and six from Group A) with adequate archival tissues." (PMID 39249118, 2024). "In murine MB49 cells, loss of FOXP3 led to smaller tumors, decreased expression of PD-L1, and increased CD8+ T cells in tumor tissues in vivo but preserved tissue expression of IFNγ, supporting loss of IFNγ responsiveness." (PMID 39099201, 2024). "On the other hand, in the tumor compartment, the number ranged from 0 to 8 for FOXP3, from 0 to 12 for CD4, and from 1 to 24 for CD8." (PMID 37567864, 2024). "According to the study’s findings, Foxp3+Treg expression increased in the majority of tumors, and while the tumor microenvironment was anaerobic, HIF-1 aggregation was present." (PMID 38919615, 2024). "Our observations from the co-culture of UPP1-overexpressing tumor cells with CD4 + T cells highlighted that UPP1 upregulation in tumor cells significantly drove the differentiation of CD4 + T cells into CD25 + FOXP3+Tregs." (PMID 38331898, 2024). "We subsequently analyzed the scores for CD3+, CD4+, CD8+, and FoxP3+ cells localizing either at the inner area of the tumor (In area) or at the tumor periphery (P area) (see the Materials and Methods section for details)." (PMID 38891095, 2024). "In the cancer microenvironment, FOXP3 is a viable target for detecting Tregs, which substantially promotes tumor immune evasion." (PMID 38376441, 2024). "The pro-tumor function of Foxp3+ Tregs involves several mechanisms: First, the inhibition of the Notch pathway." (PMID 39371092, 2024). "In the realm of KC, the CD4+CD25+Foxp3- T cell subset exerts its influence predominantly through its regulatory prowess within the intricate tumor immune microenvironment." (PMID 39267764, 2024). "TILs include T-helper cells (CD4+), cytotoxic T cells (CD8+), Foxp3+CD4+ regulatory T cells (Tregs), tumor-associated macrophages (TAMs), natural killer cells (NKCD57+), and myeloid-derived suppressor cells (MDSCs) etc." (PMID 39575251, 2024). "Immunohistochemical assays were employed to gauge the expression levels of CD4, CD8, and Foxp3, thereby providing insights into the dynamics of tumor-infiltrating lymphocytes within the tumor microenvironment." (PMID 39687297, 2024). "We discuss the prognostic significance of tumor FOXP3 expression, tumor-infiltrating FOXP3-lymphocytes, tumor FOXP3 in tumor microenvironments and the potential of FOXP3-targeted therapy." (PMID 38674427, 2024). "In tumor draining LNs, expression of FOXP3 mRNA and numbers of Tregs were similar between Scramble and ASO 6B treated mice." (PMID 39234236, 2024). "Our result showed that higher purine metabolism in tumor epithelial cells is strongly associated with markers of Treg activation (CCR8, FOXP3, and IL2RA) and levels of ADORA2A, encoding the well-known purine receptor A2AR, in Tregs." (PMID 39252976, 2024). "On the other hand, more compelling evidence that BPA can favor an immunosuppressive tumor microenvironment in the BALB–neuT model is provided by the marked increase of Foxp3+ cells observed in invasive tumors of BPA-treated mice." (PMID 38892447, 2024). "A preventative FOXP3 DNA ecombinant protein vaccine can promote immunity against Tregs in the absence of a tumor, enhancing the immune response against the tumor by targeting Tregs and Myeloid-derived suppressor cells (MDSCs)." (PMID 39198311, 2024).